GTSF1L (gametocyte specific factor 1 like)
Synonyms: C20orf65; FAM112A; dJ1028D15.4
Tractability: No criterion of Open Targets' tractability assessment is met for any kind of drug.
Gene: Protein-coding gene on chromosome 20 (43,726,164 to 43,727,002, reverse strand). Ensembl gene ENSG00000124196.
Subcellular location (Human Protein Atlas): Nucleoli
Gene Ontology:
Molecular function: protein binding; protein-containing complex binding
Genetic constraint (gnomAD): Loss-of-function variants: 3 observed, 3.13 expected, observed/expected ratio (o/e) 0.96, 90% interval 0.41 to 1.84. That is too few expected variants to judge how well the gene tolerates losing a copy. Missense variants: 169 observed, 191.13 expected, observed/expected ratio (o/e) 0.88, 90% interval 0.78 to 1. Synonymous variants: 62 observed, 72.89 expected, observed/expected ratio (o/e) 0.85, 90% interval 0.69 to 1.05.
Homologues: Orthologues: macaque GTSF1L (94% identical), pig GTSF1L (74% identical), dog GTSF1L (72% identical), mouse Gtsf1l (69% identical), rat Gtsf1l (68% identical), guinea pig GTSF1L (63% identical), tropical clawed frog gtsf2 (34% identical), zebrafish gtsf1 (22% identical), Drosophila melanogaster arx (17% identical). Paralogues in human: GTSF1 (30% identical), SNRNP48 (20% identical).
Diseases named in the same sentence as GTSF1L in open-access papers:
GTSF1L is named in the same sentence as 4 diseases in open-access papers, as found by Europe PMC text mining. Sharing a sentence is not in itself a finding about the gene and the disease. The quoted sentences say what the papers report.
cancer (2 papers, 2021). A tumor composed of atypical neoplastic, often pleomorphic cells that invade other tissues. "The correlation between GTSF1L and ICI-related genes such as PD1, PD-L1, CTLA4, and CD38 was computed by Pearson analysis in all types of cancers from the TCGA cohort." (PMID 34539641, 2021). "However, the functions of TRAV34, GTSF1L, LILRA4, and GNG8 in carcinoma remain unclear." (PMID 34844217, 2021).
GTSF1L also shares sentences with these, for which no sentence is quoted: cervical cancer (1 paper); sarcoidosis (1); tumor (1).